CGA (glycoprotein hormones, alpha polypeptide)
Diseases named in the same sentence as CGA in open-access papers (continued):
Sharing a sentence is not in itself a finding about the gene and the disease.
tumor (continued). "Thus, fragmentation of circulating CgA in tumors by local proteases may contribute to “switch on” angiogenesis, and changes in the balance of protease/antiprotease molecules in tumor tissues might represent major mechanisms for regulating the CgA activity." (PMID 31588572, 2019). "The fact that VS-1 and total-CgA are increased in patients with NENs raises the question as to whether these polypeptides are simply epiphenomena of the disease or they are somehow involved in the regulation of the tumor biology." (PMID 29723285, 2018). "We did not identify an association with tumor grade or tumor stage for either the NETest or CgA." (PMID 30564197, 2018). "Serum CgA may be a particularly valuable circulating tumor marker for early diagnosis." (PMID 30290620, 2018). "Furthermore, it should be investigated whether CgA is a suitable marker to predict survival or tumor progression in patients with NEN of the colon and rectum." (PMID 29232390, 2017). "Finally, the anti-tumor activity observed with exogenous CgA and VS-1 in the animal models suggest that pharmacological enhancement of circulating CgA and/or VS-1 in patients might represent potential therapeutic strategies that merit further investigation." (PMID 27203389, 2016). "Furthermore, a synthetic peptide corresponding to this sequence could inhibit tumor growth and recapitulate the U-shaped inhibitory effects induced by recombinant full-length CgA in the in vitro angiogenesis assay." (PMID 27683038, 2016). "Notably, antibodies against this region, which is highly conserved in mice, humans and other species, could neutralize the anti-tumor activity of both endogenous and exogenous CgA." (PMID 27683038, 2016). "Notably, the U-shaped inhibitory effects on angiogenesis mirror those on tumor mass, supporting the hypothesis that reduction of angiogenesis is indeed an important mechanism of the anti-tumor activity of CgA." (PMID 27683038, 2016). "Thus, natural CgA and recombinant CgA exerted similar anti-tumor effects in these models." (PMID 27683038, 2016). "We investigated whether circulating CgA has a regulatory function in tumor biology and progression." (PMID 27683038, 2016). "The tumor subtype could be another important determinant for CgA serum levels." (PMID 25099181, 2014). "It therefore seems likely that the CgA fragment pattern may be of value in evaluating the biologic behavior of NENs and the region-specific antibodies may be of potential use when seeking to identify individual malignant tumor phenotypes." (PMID 24260544, 2013). "Since CgA is released to the circulation it might also work as a clinical tumour marker." (PMID 10574253, 1999). "In detail, regarding CgA, different studies have reported sensitivities ranging from 32 to 92%, depending on the type of NEN, secretory condition and tumor burden." (PMID 40038821, 2025). "Questioning if those low amounts of miR directly benefit proliferation of tumor cells directly, or indirectly limits immune cell activation we performed in vitro knockdown of miR-223 in BON, a well-established CgA-expressing NEN cell line." (PMID 39851539, 2025). "Tumor cells expressed 2 or more neuroendocrine markers: synaptophysin (SYN) 100 % (4/4), CD56 100 % (4/4), and chromogranin A (CgA) 50 % (2/4)." (PMID 41305788, 2025). "Tumor markers (CA125, CA19.9, CEA), CgA, and 5‐hydroxy‐indole acetic acid (5HIAA) were found to be normal." (PMID 40542625, 2025). "In our case, immunostaining showed positive results for CgA, Syn, CD56, SSTR2, INSM1, CK and Ki-67, consistent with the histopathologic examination, confirming the neuroendocrine nature of the tumor." (PMID 40034377, 2025). "Immunophenotypic analysis has demonstrated that tumor cells express epithelial markers CK and CK20 and neuroendocrine markers CD56, Syn, and CgA." (PMID 41245381, 2025). "Factors including tumour growth rate (TGR), elevated chromogranin A (CgA) levels, and presence of lung metastases were also predictive of PFS or OS." (PMID 39061146, 2024).
tumor (continued). "Among biomarkers, CgA (HR = 7.1; P = 0.0001), ALP (HR = 4.9; P = 0.2), number of prior systemic treatment divided by time from diagnosis (HR = 1.2; P = 0.1) and primary tumor site (HR = 1.3; P = 0.007) were significant predictive features." (PMID 38948061, 2024). "Survival analysis emphasizes the need for adapted response criteria, involving combined evaluation of CgA, ADC values, and tumor size for monitoring CAPTEM response in hepatic metastasized NETs." (PMID 38613843, 2024). "LCNEC with rhabdoid features often diffusely expresses the neuroendocrine markers Syn, CgA and CD56, and tumor cells express epithelial markers." (PMID 38374950, 2024). "Multiple image-based features including total and organ-specific tumor volume and SSTR density along with clinicopathological biomarkers including Ki-67, chromogranin A (CgA) and alkaline phosphatase (ALP) were analyzed with respect to the PRRT response." (PMID 38948061, 2024). "Our study, among the first to assess multiparametric MRI for monitoring CAPTEM response in hepatic metastasized NETs, suggests the importance of combined evaluation of CgA, ADC values, and tumor size." (PMID 38613843, 2024). "NEC often diffusely expresses the neuroendocrine markers CgA, Syn and CD56, and tumor cells express epithelial markers, which are helpful for the diagnosis of NEC with large-cell and/or rhabdoid features." (PMID 38877473, 2024). "The NETest value (HR: 1.032, 95% CI: 1.003–1.062, p = 0.033) and high-risk NETest category (HR: 10.5, 95% CI: 1.35–81.7, p = 0.025) were independent predictors of PFS, along with presence of lung metastases, CgA levels > 10 × ULN, and tumour growth rate (TGR)." (PMID 39061146, 2024). "Tumor cells in the epithelial and mesenchymal regions were negative for DOG-1, CD34, S-100, SOX-10, STAT 6, SMA, C-Kit, Calretinin, Syn, CgA, TTF-1, ER, and PR." (PMID 37658451, 2023). "Overall, 78 (77.2%) patients needed additional immunohistochemical staining, particularly for CgA, Syn, CDX2, and CK, to confirm the neuroendocrine origin of the tumors and to detect the primary tumor site in those considered occult at initial diagnosis." (PMID 37338723, 2023). "Immunohistochemistry showed that tumor cells expressed neuroendocrine markers (CD56, CgA, or Syn), TTF-1, and CK." (PMID 37608278, 2023). "According to the latest recommendations of the European Neuroendocrine Tumor Society (ENETS), CgA can help diagnose and monitor the course of the disease and detect progression and recurrence." (PMID 37444393, 2023). "Serum chromogranin A (CgA) and neuron-specific enolase (NSE) measurements have traditionally been considered as tumor markers for NENs." (PMID 37568540, 2023). "The tumor cells were characterized based on their IHC reactivity to cytokeratin (AE1/AE3 or CAM 5.2) and neuroendocrine markers, including CgA, synaptophysin, and CD56." (PMID 37867522, 2023). "This is in line with our results obtained from ROC analyses showing the limited accuracy of CgA and NSE regarding the detection of a primary tumor site." (PMID 37686593, 2023). "In order to identify cofactors influencing our observations, we analyzed tumor proliferation rates, LDH level, NSE level, and CgA concentrations at primary diagnosis." (PMID 38260136, 2023). "CgA appears as a valuable biomarker in PC, particularly in CRPC, to detect neuroendocrine differentiated tumours or subpopulations." (PMID 36527470, 2023). "Immunohistochemical staining of the tumour was positive for Renin, CD34, Vimentin, and synaptophysin (Syn) and negative for somatostatin receptor 2 (SSTR2) and chromogranin A (CgA)." (PMID 35303838, 2022). "Interestingly, recent studies have shown that integrins and neuropilin-1 may also act as important receptors for CgA, vasostatin-1, CgA1-373, and other fragments, in endothelial cell biology, cardiovascular function, angiogenesis, wound healing, and tumor growth." (PMID 36559048, 2022).
tumor (continued). "The biopsy results revealed a mesenchymal malignant tumor, tumor cell cytoplasm transparent or red staining, some showed acinar arrangement, tumor cell immunophenotype: CK (−), Vim (+), CD34 (+), MyoD1 (plasma +), SMA (focal +), CD56 (−), CgA (−)." (PMID 36467475, 2022). "The routinely used immunochemical markers CgA, synaptophysin and CD56 have limitations of being single analytes and their presence in non-tumour tissue." (PMID 36362433, 2022). "The differences in levels of seven EMT-associated markers, Ki-67, DAXX, CD24, CD44, vimentin, laminin and PDX1 plus CgA and NSE (neuroendocrine markers) enabled a distinct molecular signature for each tumour grade to be generated." (PMID 36362433, 2022). "A few differentially expressed genes between the PitNET subtypes also correlate with tumor size (CACNA2D2, CGA, KRT8, RALGAPA2) suggesting a potential role in tumor growth." (PMID 34758873, 2021). "prospectively analyzed the concordance between CgA variation and RECIST criteria for tumor response in 39 metastatic well-differentiated GEP-NET patients." (PMID 34868938, 2021). "Elevation of circulating CgA level can be detected in gastroenteropancreatic (GEP)-NET patients and has been shown to correlate with tumor burden." (PMID 34868938, 2021). "prospectively monitored CgA levels for GEP-NET patients with metastasis or residual tumors and analyzed the predictive role of change of CgA level for tumor progression and regression." (PMID 34868938, 2021). "The mass was diagnosed as PGL by postoperative immunohistochemical tests (neuroendocrine markers (CgA, CD56, SYN) were positive) and by a chest enhanced CT scan (uniform enhancement of the tumor)." (PMID 32384867, 2020). "Tumor samples in the present study had been stained for markers including NUT, P63, P40, TTF-1, keratin, CK7, Syn, CD56, CgA, CD34, CD117, EGFR, and Ki-67." (PMID 32149149, 2020). "The literature states that various tumor markers—including neuron-specific enolase (NSE) and chromogranin A (CgA)—have been evaluated as sources for detecting NETs and as indicators of tumor development and response to therapy." (PMID 32563832, 2020). "Syn was expressed in almost all neoplasms containing NEC components (98.3%), while the positive rates of CgA and CD56 were much lower (62.8 and 66.7%, respectively)." (PMID 32811471, 2020). "CgA and the transcription factor ASCL-1, along with other neuroendocrine biomarkers, are often used to assess tumor burden and response to therapy." (PMID 33114525, 2020). "There was also a correlation between serum CgA levels and tumor progression: elevated serum CgA levels were reported in 83% of GEP-NETs and elevated serum CgA levels were present in 100% of cases with liver metastasis." (PMID 32020844, 2020). "CK is the main tag of the simple and glandular epithelium, SYN, CgA, and CD56 are used to identify tumors arising from neural and neuroendocrine tissues, and positivity for insulin provides tumor-specific confirmation of the disease." (PMID 32009878, 2019). "In addition to its role in tumor diagnosis, CgA is currently the most used liquid biomarker in the follow-up of NETs, as its concentration well correlates with disease progression and response to treatment and a correlation between tumor burden and serum CgA has been proven." (PMID 31382663, 2019). "First, the in vitro activity of OCT was tested in BON-1 cells, which express SST1, SST2, and SST5: OCT inhibited cAMP accumulation, CgA secretion, and MAP kinase activity, Akt-phosphorylation and cell growth, and tumor growth." (PMID 31412614, 2019). "Other biomarkers that help identify tumor source are cytokeratin, epithelial membrane antigen, glial fibrillary acidic protein (GFAP), and CgA." (PMID 30250431, 2018). "The published literature reported that the tumor cells are positive for calcitonin (100%, 11/11), HMB-45 (90.1%, 10/11), CgA (54.5%, 6/11), CEA (36.4%, 4/11), S-100 (36.4%, 4/11), and CK (36.4%, 4/11)." (PMID 30424779, 2018).
tumor (continued). "In principle, detection of CgA serum levels can diagnose NEN and predict tumor growth or prognosis in patients with some types of NEN." (PMID 29232390, 2017). "In our study, we cannot highlight any correlation between cell viability or CgA secretion responses to everolimus and/or SSAs treatments and the WHO grade or Ki67 index of the initial tumor." (PMID 28454119, 2017). "Thus, the induction of PN-1 by CgA may contribute to its anti-angiogenic and anti-tumor activities." (PMID 27683038, 2016). "By immunohistochemical examination, the tumor was strongly positive for HMB-45, focally positive for c-Kit (CD117), and negative for vimentin, S-100, AE1/AE3, CK-7, CK-18, CD-10, RCC antigen, CgA, DOG-1, EMA, smooth muscle actin (SMA), and synaptophysin." (PMID 27858882, 2016). "Immunohistochemistry demonstrated diffuse membrane positivity of the tumor cells for vimentin, FLI1 and CD99 and negativity for CKpan, CgA, Syn, CD117, HMB45, S100, CD20 and CD3." (PMID 25780425, 2015). "During the past several decades, a growing body of evidence has demonstrated that CgA is released in abnormal amounts by many neoplastic neuroendocrine cells, which may affect the various components of the tumor stroma and contribute to the regulation of tumor growth and progression." (PMID 25894842, 2015). "The immunohistochemical report showed that tumor cells were stained positive for cytokeratin AE1/3, cytokeratin CAM5.2, chromogranin A (CgA), synaptophysin (Syn), CD56 antigen, CDX-2 and Ki-67 (approximately 30-50%)." (PMID 24884973, 2014). "The tumor cells are positive for CD56 and CgA, which is helpful to distinguish from the CDC tumor cells." (PMID 23866935, 2013). "Though the sensitivity of CgA depends upon the NEN type and tumour burden, patients with NEN-LM tend to have significantly higher CgA concentrations than those without metastases." (PMID 22319653, 2012). "There were significant differences between the two groups for the measured levels of tumour markers hCGβ, AFP, CgA, and survival as measured from the time of diagnosis, but not for MIB-1 scores." (PMID 18577995, 2008). "A number of putative tumour markers are measured in NET patients, with CgA having the highest expression in NETs and being considered the most useful diagnostic and prognostic marker." (PMID 18577995, 2008). "There were significant differences between the two groups for the measured tumour markers AFP, hCGβ, CgA, MIB-1, and survival as measured from the time of diagnosis." (PMID 18577995, 2008). "The relationship between the expressions of pS2 was studied with CgA expression, clinical stage (TNM) and tumour grade (Gleason system)." (PMID 15588310, 2004). "Tyrosine hydroxylase labelling was extensive and present in all tumour cells, while CgA and NESP55 labelling was more limited and present in a subpopulation of tumour cells." (PMID 12771991, 2003). "The NE tumour cell lines GOT1 and BON were both positive for VMAT1 and 2, SV2 and CgA immunocytochemically." (PMID 14520475, 2003). "Tumor cells tested negative for SMARCA4 but were positive for Chromogranin-A(CgA), Synaptophysin (SYN), Insm-1, TTF-1 (partial), and Ki67 (90%)." (PMID 40661782, 2025). "Immunohistochemical staining plays a crucial role in diagnosing PGL, as it typically demonstrates that tumor cells are positive for CgA, Syn, NSE, and CD56 while negative for epithelial markers such as CK, EMA, and GPC3." (PMID 40978045, 2025). "Neuroendocrine cells within the tumor express CD56, Syn, or CgA." (PMID 40575627, 2025). "Immunohistochemical staining showed that the tumor tissue was positive for CgA, Syn, S - 100, CD10, and CD34, but negative for AFP, cytokeratin 19 (CK19), CK7, GS, GPC3, HSP70, with a Ki-67 labeling index of 2%." (PMID 40978045, 2025). "Half of the patients showed a relevant decrease in CgA, with a maximum decline from 6661.0 to 1300.0 ng/ml (patient No. 10), while the other half showed stable tumor markers." (PMID 40202686, 2025).
tumor (continued). "Immunophenotyping: tumor cells were diffusely strongly positive for P16, and expressed 2 or more neuroendocrine markers, with positive rates of CD56 100% (4/4), synaptophysin (SYN) 100% (4/4), and chromogranin (CgA) 50% (2/4)." (PMID 41305788, 2025). "Being neoplasms of neuroendocrine nature, SCCOPT and ovarian metastases from SCC both show positive immunohistochemistry for typical neuroendocrine markers such as NSE, synaptophysin, CgA, and CD56." (PMID 41464736, 2025). "The tumor cells exhibited positive expressions for the epithelial cell markers AE1/AE3, along with the neuroendocrine markers, synaptophysin (Syn), chromogranin (CgA), and CD56 as based on results from immunohistochemical staining." (PMID 40666092, 2025). "Immunohistochemical analysis revealed the following results: Tumor cells were negative for Ckp, positive for desmin and actin, negative for myogenin, positive for MyoD1, and negative for CgA, S-100, Syn, h-caldesmon, SMA, Sox-10, Pax-8, and GATA3." (PMID 39139286, 2024). "Prognostic factors for recurrence included stage at diagnosis, p-CgA and Ki-67 index while tumor grade did not predict recurrence." (PMID 38201631, 2024). "In addition, proteins less abundant in the tumor, such as basigin, N-WASP, Galectin-3 (Gal-3), and chromogranin-A (CgA), were identified in this functional network." (PMID 39195201, 2024). "Due to its high specificity, it can be used as a tumor marker for ANENs; however, the role of CgA in monitoring disease recurrence has not yet been established." (PMID 39456535, 2024). "The tumor cells were negative expression of CgA, CD56, CK5/6, CK20, Myogenin, MyoD1, Desmin, CEA, S100, CK8/18, CDX2, CD20, CD5, CD3, CD79a, LCA and HMB45." (PMID 38877473, 2024). "Together with the most sensitive and specific markers, namely CgA and Syn, recently, a novel biomarker, INSM1, has been proposed as an accurate indicator of NE differentiation to support NEN diagnosis, in particular, in poorly differentiated neoplasms." (PMID 38980337, 2024). "In all conditions, the xenografted tumor stained positively for synaptophysin and staining for CgA was not noted." (PMID 39649120, 2024). "Additionally, we analyzed the predictive values of CgA, NSE and LDH for the detection of a primary tumor site by means of ROC analysis." (PMID 37686593, 2023). "CgA expression correlates with the amount of secretory vesicles in neuroendocrine cells, and serum CgA levels correlate with the release of the contents of these vesicles, including from PPGL tumor cells." (PMID 36472300, 2023). "The tumor cells express SYP, CgA, glucagon and often pancreatic polypeptide (PP)." (PMID 36830839, 2023). "Additionally, CGA-TSHR, EFNA2-EPHA1, FGF17-FGFR2, FGF3-FGFR2, and TAC4-TACR1 were high-scoring tumor-to-stroma signaling interactions in both primary and metastatic lesions." (PMID 36676129, 2023). "The EWS tumor cells usually express CD99, vimentin, synaptophysin (Syn), and neuron-specific enolase (NSE) but do not express common antigen (LCA), CD20, and chromaffin granin (CgA)." (PMID 37469664, 2023). "The tumor cells are positive for neuroendocrine markers, such as Syn, CgA and NSE; nevertheless, they are negative for HMB-45, Malen-A, CD34." (PMID 36800595, 2023). "CgA, ISLET-1 and serotonin were significantly less frequently assessed in the sera or tumor tissues of patients belonging to the NEC cohort, whereas CD56 was significantly more often stained in tumor tissues of patients with NEC." (PMID 37686593, 2023). "While changes of CgA levels in individual patients can be useful as surrogate for tumor progression, the levels do not reflect the aggressiveness of the tumor and further most aggressive G3 tumors often express less CgA compared to well differentiated tumors." (PMID 37318593, 2023).